RNU6-118P (RNA, U6 small nuclear 118, pseudogene)
Gene: Small nuclear RNA gene on chromosome 11 (62,815,966 to 62,816,067, reverse strand). Ensembl gene ENSG00000252361.
Homologues: Orthologues: chimpanzee U6 (100% identical), macaque U6 (95% identical), guinea pig U6 (84% identical), rat U6 (81% identical), pig U6 (78% identical), dog U6 (77% identical), rabbit U6 (75% identical). Paralogues in human: RNU6-1263P (85% identical), RNU6-281P (85% identical), RNU6-463P (85% identical), RNU6-574P (85% identical), RNU6-657P (85% identical), RNU6-1060P (84% identical), RNU6-1122P (84% identical), RNU6-116P (84% identical), RNU6-15P (84% identical), RNU6-33P (84% identical), RNU6-474P (84% identical), RNU6-536P (84% identical), and 1286 more.